PDGFRA (platelet derived growth factor receptor alpha)
Diseases named in the same sentence as PDGFRA in open-access papers (continued):
Sharing a sentence is not in itself a finding about the gene and the disease.
neuroblastoma (12 papers, 2015 to 2025). Neuroblastoma (NB) is the most common solid, extracranial childhood tumor. "In addition, we validated the expression of the mesenchymal marker PDGFRA that was identified to be significantly highly expressed in high-risk neuroblastoma cluster (nC3)." (PMID 34493726, 2021). "Using SH-SY5Y neuroblastoma cells, transfectable with miR mimics, we demonstrated that PDGFRA protein expression decreased by about 30% with miR-34c-5p mimic and by 99.96 and 32% with miR-200a-3p and miR-200b-3p mimics, respectively." (PMID 29305721, 2018). "In addition, the Ch-IP assay showed that c-Jun bound to RARβ, TrkB and PDGFRα promoters, which are crucial to RA-induced neuroblastoma cell differentiation." (PMID 40149013, 2025). "Furthermore, analysis of PDGFRA mRNA expression in the Cancer Cell Line Encyclopedia showed that neuroblastoma cell lines express relatively high levels of this RTK, ranking in 2nd position in average overall." (PMID 34716856, 2022). "In addition, it has been reported that serum starvation leads to upregulation of PDGFRα through the inhibition of the AKT/FOXO pathway in neuroblastoma cells and MEFs39." (PMID 33568640, 2021). "Additionally, we demonstrated that PHF14 depletion resulted in upregulation of platelet derived growth factor receptor-alpha (PDGFRα) mRNA and protein in neuroblastoma SHSY-5Y cells and led to increased sensitivity to treatment with the PDGFR inhibitor Sunitinib." (PMID 36359362, 2022). "More importantly, RTKs that have remained poorly studied in the context of neuroblastoma pathogenesis, such as DDR2 and PDGFRA, are now revealed as very robust and potentially critical modulators of neuroblastoma." (PMID 34716856, 2022). "ALK, FGFR1, RET, PDGFRA, DDR2, EGFR, and IGF1R were enriched in endosomes from two or more neuroblastoma cell lines, but there were profound differences among cell lines." (PMID 25884760, 2015). "Several relatively non-specific inhibitors of PDGFRA (i.e., imatinib and sunitinib) are currently in clinical trials, and as more specific and potent PDGFRA inhibitors are developed, our findings support preclinical testing in neuroblastoma tumor models." (PMID 34716856, 2022). "Stage 2B neuroblastoma was more heterogeneous in DBH and PHOX2B expression, with all cells lacking expression of PRRX1 and very few cells positive for PDGFRA." (PMID 34493726, 2021).
diabetes (11 papers, 2015 to 2025). "Therefore, it is necessary to explore the reason for the high abundance of PDGFRα+ cells in colon smooth muscle tissue caused by diabetes." (PMID 34755491, 2021). "The hyperfunction of colonic PAR2 induced by diabetes is involved in the process of colonic PDGFRα+ cell proliferation, which is mediated by the PI3K/Akt signaling pathway." (PMID 34755491, 2021). "The results showed that PDGFRα and Ki‐67 coexpression was significantly increased in the diabetes and PAR2 agonist groups compared with the control group." (PMID 34755491, 2021). "These phenomena demonstrate that diabetes significantly increased PDGFRα and PAR2 coexpression in the colonic muscle layer." (PMID 34755491, 2021). "In summary, diabetes induces the proliferation of PDGFRα+ cells in the colon, leading to an imbalance between ICCs and PDGFRα+ cells in the colonic SIP syncytium, which leads to diabetic slow transit constipation." (PMID 34755491, 2021). "The aim of this study was to identify PDGFRα and c-kit immunoreactive cells in the colon of rats with streptozotocin/nicotinamide-induced diabetes mellitus type 2, as well as to determine their distribution in relation to smooth muscle cells and enteric nerve structures." (PMID 36837509, 2023). "Moreover, to further clarify the proliferation state of PDGFRα+ cells in colon muscle tissue in diabetes, Ki‐67 expression in colon muscle tissue was measured in STZ‐treated mice." (PMID 34755491, 2021). "Our previous study indicated that streptozotocin (STZ)‐induced diabetes leads to colonic platelet‐derived growth factor receptor‐α‐positive (PDGFRα+) cell proliferation accompanied by slow colonic transit in mice; however, the mechanism of this effect is unclear." (PMID 34755491, 2021). "The diabetes‐induced increase in PAR2 can promote colonic PDGFRα+ cell proliferation and can stimulate SK3 channel activation on the cell membrane of PDGFRα+ cells, which may lead to colonic motility disorders." (PMID 34755491, 2021). "The results indicate that PAR2 is involved in the proliferation of PDGFRα+ cells through the PI3K/Akt signaling pathway in the colon of STZ‐induced diabetic mice, which may contribute to the slow transit and constipation that are associated with diabetes." (PMID 34755491, 2021). "However, whether PAR2 contributes to colonic motility disorder induced by diabetes is currently unclear, and thus, coexpression of PDGFRα and PAR2 in colonic muscle tissues was investigated in STZ‐induced diabetic mice." (PMID 34755491, 2021). "In the context of diabetes mellitus (DM), the upregulation of m6A modification mediated by METTL3 suppresses the expression of key genes, including PKC-η, FAT4, and PDGFRA." (PMID 41315216, 2025). "However, at present, there are no reports that diabetes can affect colon PDGFRα+ cell proliferation induced by PAR2." (PMID 34755491, 2021).
diffuse midline glioma (11 papers, 2017 to 2025). A diffuse glioma that arises from the midline structures of the central nervous system. "While some studies have associated PDGFRA amplification with poor survival (PS) outcomes, particularly in diffuse midline gliomas, its predictive value as an independent biomarker in GBM remains debated." (PMID 40628732, 2025). "The remaining two patients progressed rapidly—an H3K27M mutant diffuse midline glioma with PDGFRA mutation treated with ponatinib and then regorafenib, and an MB with FGFR3 mutation given pazopanib, ifosfamide and doxorubicin." (PMID 38844796, 2024). "Most recently, a retrospective study introduced three prognostic markers to refine diffuse midline glioma prognosis: the loss of 17p, PDGFRA amplification and a complex chromosomal profile." (PMID 33557011, 2021). "Notably, SOX10, a key transcription factor associated with oligodendroglial differentiation and PDGFRA regulation, was up-regulated in both DCG and H3 K27M-mutant diffuse midline glioma, suggesting their developmental and biological commonality." (PMID 28852847, 2017). "Notably, all DCGs were clustered into either of two methylation groups; two DCGs with H3F3A K27M mutation were clustered together with diffuse midline glioma, K27M-mutant (the “K27” group), whereas all of the other 12 DCGs were clustered in the “RTK I (PDGFRA)” group." (PMID 28852847, 2017). "Consequently, we compared the methylation profiles of K27M-mutated diffuse midline gliomas (including DIPG) to G34R-mutated tumors and well-characterized supratentorial tumors without mutation in histone H3 genes, i.e. MYCN and PDGFRA tumor subgroups." (PMID 30396367, 2018).
ischemic stroke (11 papers, 2012 to 2025). A stroke disorder caused by obstruction of blood flow to the brain, due to thrombotic (local blood clot formation) or embolic (due to a blood clot or other material traveling from another site) event. "To determine if Mac-1 deficiency directly affects PDGFRα activation during ischemic stroke, we first examined the localization of the PDGFRα by confocal microscopy." (PMID 28725968, 2017). "PDGFRβ+ fibroblasts co-expressing PDGFRα, which are essentially associated with the large pial penetrating vasculature, and PDGFRβ+ pericytes, which are essentially associated with parenchymal microvasculature, both have been reported to contribute to fibrotic scar formation after ischemic stroke." (PMID 38769116, 2024). "TPA-mediated activation of PDGF-CC/PDGFRα signaling in the NVU during ischemic stroke in mice induces opening of the BBB and augments brain injury." (PMID 39808499, 2025). "This study suggests targeting myofibroblast expansion by inhibition of PDGFRα signaling as a potential novel post-acute target to foster CNS repair after ischemic stroke." (PMID 39808499, 2025). "Our analysis revealed that PDGFRα+ and perivascular tdTomato+ cells (i.e. deriving PDGFRβ+ cells) constitute two distinct populations at the lesion site 1 week after ischemic stroke." (PMID 38769116, 2024). "Imatinib can effectively decrease BBB permeability by blocking the signaling of platelet-derived growth factor receptor alpha (PDGFR-α) in ischemic stroke." (PMID 33952281, 2021). "Following ischemic stroke, a significant increase in tissue plasminogen activator-dependent cerebrovascular permeability occurs via signaling through the activated PDGFRα pathway and LRP1 pathway." (PMID 30186167, 2018). "Importantly, we found PDGFRα inhibition to be effective in enhancing functional recovery when initiated 24 hours after ischemic stroke." (PMID 39808499, 2025). "Based on this, we hypothesize that modulation of the myofibroblast response, by targeting signaling via PDGFRα, contributes to the beneficial effect seen on neurological and functional outcome with imatinib after ischemic stroke." (PMID 39808499, 2025). "However, activation of PDGFRα+ perivascular astrocytes exacerbates microvascular impairments after ischemic stroke." (PMID 38769116, 2024). "Toward that goal, the recent phase II clinical trial testing the safety of the PDGFRα antagonist Imatinib in patients treated with intravenous thrombolysis after ischemic stroke has demonstrated that Imatinib is safe following thrombolysis and improves neurological outcomes." (PMID 28725968, 2017). "However, PDGF-B could activate PDGFRα, which has been shown to exacerbate vascular permeability after ischemic stroke by activating perivascular astrocytes." (PMID 38769116, 2024). "Finally, it is also interesting to speculate that if the increased permeability associated with PDGFRα signaling in the NVU does act to promote CNS inflammation, then the benefits of inhibiting this pathway may be wider than just in ischemic stroke." (PMID 28725968, 2017). "Since both TBI and ischemic stroke share the common pathophysiologic mechanisms of loss of BBB control and the development of cerebral edema, we hypothesized that, as is the case with ischemic stroke, PDGFRα signaling might also play a role in TBI." (PMID 26500491, 2015). "Using both a cell-based PDGFRα activation assay and a photothrombotic model of ischemic stroke, we show that both Mac-1 and LRP1 are required for efficient activation of PDGF-CC by tPA and the subsequent phosphorylation of the PDGFRα." (PMID 28725968, 2017). "Following ischemic stroke, there is a significant tPA-dependent increase in cerebrovascular permeability via signaling through the PDGF-CC/PDGFRα pathway." (PMID 28725968, 2017).
ischemic stroke (continued). "The PDGFRα is localized to astrocytes in the NVU, and blocking this pathway with either the PDGFRα antagonist Imatinib or neutralizing antibodies to PDGF-CC reduces BBB dysfunction and improves outcome after ischemic stroke." (PMID 26500491, 2015).
medulloblastoma (11 papers, 2013 to 2026). A malignant, invasive embryonal neoplasm arising from the cerebellum. "The expression of PDGFRα has also been demonstrated in medulloblastomas and primitive neuroectodermal tumors, and an increase in PDGFRα gene copy numbers seems to be associated with poor survival in these tumors." (PMID 26248280, 2015). "In medulloblastoma, increased copy number of the platelet-derived growth factor receptor alpha (PDGFRα) and overexpression of the epidermal growth factor receptor (EGFR) are associated with poor outcome." (PMID 25596739, 2015). "Importantly, both PDGFRα and c-Kit are upregulated in medulloblastoma, and PDGFRβ was shown to be critical for migration and invasion of medulloblastoma cells." (PMID 31539380, 2019). "Therefore, we started to screen the expression of VEGFR1-3, PDGFRα/β, MET, FGFR1-2 and ErbB1-4 on the cell surface of 5 medulloblastoma cell lines." (PMID 26496080, 2015). "Various receptor tyrosine kinases (RTK’s) are expressed in medulloblastoma, including vascular endothelial growth factor receptor-2 (VEGFR-2), platelet-derived growth factor receptor α (PDGFRα), hepatocyte growth factor receptor (MET) and epidermal growth factor receptor 2 (ErbB2)." (PMID 26496080, 2015). "As a comparison, we assessed two medulloblastoma cases (NMB361 and NMB795), which showed nuclear staining for SMARCB1 and were negative for both PDGFRα and FGFR1." (PMID 27783942, 2016).
breast tumor (10 papers, 2011 to 2023). "P-AKT1, p-CREB, and PDGFRα levels were substantially elevated in almost all of the 12 breast tumor tissues tested, and in which the PTEN levels were significantly decreased as compared with those in corresponding para tumor tissues." (PMID 33568640, 2021). "The receptor for PDGF-CC, i.e., PDGFRα, is exclusively expressed by mCAFs, identifying this subgroup as responsible for the specification of ERα-negativity in breast tumors." (PMID 30514914, 2018). "To better understand the role of invadopodia and PDGFRα in metastasis, we utilized a subcutaneous tumor implantation model in which Twist1-expressing human breast tumor cells carrying shRNAs against PDGFRα or Tks5 were injected subcutaneously in nude mice." (PMID 21725138, 2011). "Additionally, ablation of tumour stromal neuron glia antigen‐2 (NG2)+ and PDGFRα+ pericytes significantly reduces breast tumour volume in preclinical studies." (PMID 33152121, 2021). "Indeed, CD146 is absent from mCAFs and exclusively expressed by vCAFs in our classification, supporting specific targeting of PDGFRα+/CD146− CAFs as an attractive strategy to sensitize basal-like breast tumors to endocrine therapy by conversion into an ERα+ phenotype." (PMID 30514914, 2018). "When PDGFRA, PDGFRB, and PDGF-CC protein expression levels were observed in the breast tumor samples, PDGF-CC expression was found to be correlated with poor prognosis and PDGFRA was associated with lymph node metastasis and recurrence." (PMID 36979654, 2023). "Taken together, these results indicate that a NG2+PDGFRα+gp38+ stromal cell population isolated from primary human breast tumours are positive and negative for markers that define stromal cell lineage and a subpopulation of TASCs express syndecan‐2." (PMID 33152121, 2021). "However, striking similarities between mouse and human breast tumours were found in terms of the distribution and morphology of stromal fibroblasts expressing ASMA, PDGFRα, and FSP1, respectively." (PMID 22432595, 2012).
idiopathic hypereosinophilic syndrome (10 papers, 2004 to 2025). "In a series of 16 patients with idiopathic hypereosinophilic syndrome, a novel fusion of PDGFRA and FIP1L1 has been reported." (PMID 14710199, 2004). "Although the FIP1L1–PDGFRA fusion—well established in idiopathic hypereosinophilic syndrome—has not been identified in IFPs, it illustrates how PDGFRA dysregulation can drive marked eosinophilic proliferation." (PMID 41562800, 2025).
renal cell carcinoma (10 papers, 2005 to 2025). ": This study aimed to assess the expression of platelet-derived growth factor receptors alpha and beta (PDGFRα/β) in primary tumor cells of patients with renal cell carcinoma (RCC)." (PMID 40434293, 2025). "Axitinib is an inhibitor of VEGFR1, VEGFR2, VEGFR3, PDGFRα, and PDGFRβ, approved by the U.S. FDA in 2012 for the second-line therapy for advanced renal cell carcinoma (RCC)." (PMID 37377855, 2023). "CCL22, CRP, ICAM1, IFNG, PDGFRA, TGFB1 and TNFSF11 have been confirmed to be involved in the malignant progression and metastasis of renal cell carcinoma through different biological mechanisms." (PMID 34187413, 2021). "Pieces of evidence such as the drug combination of sunitinib targeted PDGFRA and sorafenib targeted KIT, was proved to be successful for renal cell carcinoma in clinical trial phase 3." (PMID 32523951, 2020). "For example, the immunotherapeutic drug pembrolizumab was used in combination with lenvatinib, a targeted drug that inhibits the activity of VEGFR, FGFR, PDGFRα, KIT and Ret, demonstrated promising anti-tumor effect in patients with renal cell carcinoma or endometrial cancer." (PMID 31673068, 2019).
lymphoma (9 papers, 2007 to 2025). A malignant (clonal) proliferation of B- lymphocytes or T- lymphocytes which involves the lymph nodes, bone marrow and/or extranodal sites. "Imatinib, a PDGFRA-selective tyrosine kinase inhibitor, has been validated to be effective in blocking lymphoma growth in both human xenograft and murine allograft models." (PMID 36281462, 2022). "Another study showed that PDGFR inhibition was a rational and effective therapeutic agent for nucleophosmin-anaplastic lymphoma kinase (NPM-ALK) fusion lymphomas, suggesting that ALK might be a target of activating mutations of the genes encoding PDGFRA." (PMID 32005261, 2020).
neurofibromatosis type 1 (9 papers, 2010 to 2026). A clinically heterogeneous, neurocutaneous genetic disorder characterized by cafe-au-lait spots, iris Lisch nodules, axillary and inguinal freckling, and multiple neurofibromas. "Although the majority of GISTs are sporadic, there are forms that are associated with a variety of syndromes including Carney-Stratakis syndrome and neurofibromatosis type 1, as well as a subset of familial GIST syndromes that are caused by germline mutations in KIT or PDGFRA." (PMID 26246933, 2015). "Gene expression-based subtypes are: proneural (PN) aberrations in the platelet-derived growth factor receptor alpha (PDGFRA), mesenchymal (MES) aberrations in neurofibromatosis type I (NF1), and classical (CL) aberrations in epidermal growth factor receptor (EGFR)." (PMID 31484350, 2019). "Similarly, NF1 gene mutations are commonly seen in neurofibromatosis type 1-associated GISTs and are characterized by a distinct molecular profile lacking KIT or PDGFRA mutations." (PMID 40282558, 2025). "The majority of GISTs are driven by sporadic somatic KIT or PDGFRA mutations rather than inflammation-associated carcinogenesis; rare hereditary and syndromic forms of GIST (e.g., familial KIT/PDGFRA mutations, Carney–Stratakis syndrome, and neurofibromatosis type 1–associated GIST) do exist." (PMID 41517566, 2026).